GFI1 (growth factor independent 1 transcriptional repressor)
Diseases named in the same sentence as GFI1 in open-access papers (continued):
Sharing a sentence is not in itself a finding about the gene and the disease.
myelodysplastic syndrome (7 papers, 2017 to 2025). A clonal hematopoietic disorder characterized by dysplasia and ineffective hematopoiesis in one or more of the hematopoietic cell lines. "Growth Factor Independence 1 (GFI1) is a transcription factor with an important role in the regulation of development of myeloid and lymphoid cell lineages and was implicated in the development of myelodysplastic syndrome (MDS) and acute myeloid leukaemia (AML)." (PMID 35008835, 2021). "We previously reported that a coding single nucleotide polymorphism (SNP) in the human GFI1 (rs34631763, denominated as GFI1-36N) predisposes carriers to myelodysplastic syndrome (MDS) and acute myeloid leukaemia (AML) and influenced their prognosis." (PMID 34760702, 2021). "Finally, GFI1 is a C2H2 type zinc finger transcriptional repressor implicated in the pathogenesis of AML and myelodysplastic syndrome (MDS)." (PMID 37297004, 2023). "Interestingly, low levels of Gfi1 have been associated with a worse outcome of both chronic myeloid leukemia and AML resulting from a myelodysplastic syndrome (MDS)." (PMID 29925903, 2019).
myeloid leukemia (7 papers, 2013 to 2025). A clonal proliferation of myeloid cells and their precursors in the bone marrow, peripheral blood, and spleen. "In order to obtain a cross-entity assessment that is not only focused on AML and to obtain an initial overview of the effects of the polymorphism, we addressed this question in the human myeloid leukemia cell line K562, in which we knocked in a GFI1-36N variant." (PMID 39857691, 2025). "We further assessed the effect of GFI1 knockdown on Doxo-induced cell death in myeloid leukemia cell lines U937 and HL-60, both of which expressed high levels of endogenous GFI1." (PMID 24023884, 2013). "Over-expression of Gfi1 and Gfi1b have been observed in induced and naturally occurring lymphoid and myeloid leukemias in mice and humans respectively." (PMID 23308270, 2013). "Evidence for a role of GFI1 in AML emerged almost a decade ago when studies first indicated that the GFI1 gene was expressed in several human myeloid leukemia cell lines as well as cells from patients with different types of myeloid leukemia including AML." (PMID 31508375, 2019). "In human myeloid leukemia, low GFI1 levels correlate with an inferior prognosis." (PMID 29925903, 2019). "To study the relation between Gfi1 expression levels and myeloid leukemia, we have generated humanized GFI1 “knock in” expressing the Human GFI1 gene at WT levels (called “KI” mice) and mice expressing only a reduced level of GFI1 called “KD”." (PMID 29925903, 2019). "Interestingly, we also found that Mx-Cre KD mice injected with MMLV and ENU and later with pIpC developed predominantly lymphoid leukemia while mice expressing a low level of Gfi1 still showed the myeloid accumulation leading to myeloid leukemia." (PMID 29925903, 2019). "Moreover, our finding that reduced Gfi1 expression levels almost exclusively orients the effect of both mutagenic agents, ENU and MMLV, towards a myeloid leukemia is additional evidence that a low Gfi1 dose predisposes for MPN or AML." (PMID 29925903, 2019). "However, the exact mechanism by which reduced Gfi1 expression levels accelerate or induce myeloid leukemia remains unclear and poorly understood." (PMID 29925903, 2019). "Our studies reveal the coincident genome-wide binding of the HMG-box protein HMG20B with LSD1 and GFI1 in myeloid leukemia cells, and the functional relevance of the interaction of the coiled-coil domain of HMG20B with LSD1 in stabilizing the interaction of LSD1 with GFI1." (PMID 36171271, 2022).
colorectal cancer (6 papers, 2019 to 2022). A primary or metastatic malignant neoplasm that affects the colon or rectum. "We also identify a deletion causing GFI1 to gain an eQTL, enhancer and super enhancer in colorectal cancer and an inversion causing a gain of an eQTL in prostate cancer." (PMID 34257393, 2021). "Down-regulation of GFI1 can promote inflammation-linked metastasis of colorectal cancer, and it is a tumor suppressor gene.Currently, we proved that GFI1 was down-regulated in HCC tissues and cells." (PMID 33489916, 2020). "GFI1 has been identified as a potential therapeutic target for interfering with inflammation-induced colorectal cancer progression and spread." (PMID 33632303, 2021). "Two recent studies reported Gfi1 downregulation in colorectal cancer suggesting a tumor suppressor role in this tissue." (PMID 32630147, 2020). "Gfi1 loss of expression have been also reported in non-small cell lung carcinoma (NSCLC) and colorectal carcinoma." (PMID 32630147, 2020). "In colorectal carcinoma Gfi1 silencing influences metastasis spread." (PMID 32630147, 2020). "Future larger studies are required to confirm the link between GFI1 and TNFRSF11A and patient outcome, and to determine the role of these genes in colorectal cancer development." (PMID 30858927, 2019). "Two candidate gene markers (GFI1 and TNFRSF11A) assessed in this study were identified from a previous study led by the The Cancer Genome Atlas (TCGA) Network, and analysis was performed on 112 consecutively collected, archival FFPE colorectal cancer tumour samples." (PMID 30858927, 2019).
hearing loss (6 papers, 2012 to 2024). "We have presented a family with a complex phenotype of SCN and hearing loss that can be attributed to AD variants in two genes, GFI1 causing SCN, and MYO6 leading to hearing loss." (PMID 32066420, 2020). "First, we identified mostly reduced expression of genes previously associated with loss of function mutations linked to overt hearing loss, including Gfi1, Otog, Mafb, Sema3e, Smpx and Sptbn4, suggesting hidden and overt hearing loss share similar genetic mechanisms." (PMID 39049179, 2024). "In future studies, therefore, it will be interesting to correlate the presumably reduced levels of the Gfi1 transcription with different POU4F3 mutations and the severity of the associated hearing loss." (PMID 28053790, 2016). "As GFI1 variants have not previously been associated with hearing loss, we explored additional genetic causes for the hearing loss phenotype observed in this family." (PMID 32066420, 2020). "Upon weaning it was apparent that some of the Gfi1-NICD offspring lacked a Preyer reflex, the ear flick response to sound, indicating a hearing impairment." (PMID 25264928, 2014).
lymphoid leukemia (5 papers, 2013 to 2024). A malignant lymphocytic neoplasm of B-cell or T-cell lineage involving primarily the bone marrow and the peripheral blood. "Gfi1 is an important factor in the initiation and maintenance of lymphoid leukemias and its deficiency significantly impedes Notch dependent initiation of T-ALL in animal models." (PMID 24068942, 2013). "GFI1 is a transcriptional regulator expressed in lymphoid cells, and an “oncorequisite” factor required for development and maintenance of T-lymphoid leukemia." (PMID 29651020, 2018). "Recently, we identified Gfi1 as an important factor in the initiation and maintenance of lymphoid leukemias." (PMID 24068942, 2013).
breast carcinoma (4 papers, 2009 to 2023). "High expression of GFI1 was also associated with poor prognosis for patients with breast cancer and ovarian cancer." (PMID 35819844, 2022). "Once the epigenetic loss of Gfi1 function on prostate and breast cancer cell lines was demonstrated, the prevalence of Gfi1 methylation in primary tumors was determined by MSP." (PMID 32630147, 2020). "Seven of the 15 TME prognostic genes (NOS2, SCG2, RGS3, EMP1, PDLIM4, PCDH9, and GFI1) were involved in enhancing cell proliferation, destroying cell apoptosis, promoting cell invasion, or migration in breast cancer." (PMID 36936167, 2023). "As expected, seven of the TME prognostic genes (NOS2, SCG2, RGS3, EMP1, PDLIM4, PCDH9, and GFI1) showed dual functions in breast cancer progression." (PMID 36936167, 2023). "In this work, we have found that Gfi1 silencing by promoter hypermethylation is a common event in prostate and breast cancer." (PMID 32630147, 2020). "Gfi1 re-expression in prostate and breast cancer cell lines displaying Gfi1 epigenetic silencing decreases cell proliferation, reduced colony formation density, and tumor growth in nude mice xenografts." (PMID 32630147, 2020). "We assessed the ability of Gfi1 to function as tumor suppressor gene in prostate and breast cancer cell lines." (PMID 32630147, 2020). "In this study, we have found that Gfi1 epigenetic silencing is a common event in prostate and breast cancer." (PMID 32630147, 2020). "All these data point to Gfi1 as a potential tumor suppressor in prostate and breast cancer." (PMID 32630147, 2020). "Our data can be explained by proposing a similar role for Gfi1 in prostate and breast cancer." (PMID 32630147, 2020). "In summary, our results show for the first time the epigenetic silencing of Gfi1 in prostate and breast cancer, and that this event could be a crucial step in the development of these two-well characterized endocrine-related tumors." (PMID 32630147, 2020). "In conclusion, our findings strongly indicate that Gfi1 epigenetic silencing in prostate and breast cancer could be a crucial step in the development of these two-well characterized endocrine related tumors." (PMID 32630147, 2020). "Interestingly, significant Gfi1 promoter hypermethylation was found in four breast cancer cell lines (MDA-MB-231, MDA-MB-463, BT474 and BT549) and was unmethylated in normal breast indicating that this is not a general event." (PMID 32630147, 2020). "We have found that Gfi1 epigenetic silencing is a common event in prostate and breast cancer." (PMID 32630147, 2020). "However, little is known about the function of Gfi1 in prostate and breast cancer." (PMID 32630147, 2020). "The breast cancer cell lines MDA-MB-231 and BT-474 showing Gfi1 hypermethylated, express very low levels of Gfi1 mRNA compared with normal breast." (PMID 32630147, 2020). "Two additional targets, the growth factor transcriptional repressor GFI1 gene (target number 8) and the nuclear receptor NR2E1 gene (target number 40), were inspected to evaluate the level of methylation in early-stage breast carcinomas." (PMID 19250546, 2009). "Here we found that Gfi1 repress AAT and ACT expression in prostate and breast cancer cell lines, while did not change the expression of genes with specific functions in the hematopoietic system." (PMID 32630147, 2020).
chronic myeloid leukemia (4 papers, 2013 to 2020). "Mcl-1 is required for proliferation and survival of hematopoietic stem cells and is a transcriptional target of Gfi1 in chronic myelogenous leukemia." (PMID 30286780, 2018).
lung carcinoma (4 papers, 2020 to 2025). "Association between gene-level methylation scores (AHRR*, MYO1G, CYP1A1, FRMD4A, and GFI1*) and lung cancer risk, among ever smokers (186 matched pairs) nested in the CLUE II cohort (1989–2018)." (PMID 39544416, 2024). "For these genes, FIGNL2 and GFI1 have been studied in lung cancer; FIGNL2 promotes cell growth and tumorigenesis, while GFI1 shows methylation alteration." (PMID 40837413, 2025).
T-cell lymphomas (4 papers, 2013 to 2020). "In 1997, it was shown that the eis-1/pal-1/gfi-1/evi-5 locus serves as a target for M-MuLV proviral insertions in pre-B-cell lymphomas in Eμ-myc transgenic mice (20%) and in T-cell lymphomas in H2K-myc (75%) and Eμ-pim1 (93%) transgenic mice." (PMID 24860787, 2014). "In addition, after a latency period of 114 days, almost all of the double lck-gfi1; Eμ-pim1 transgenic mice developed T-cell lymphoma, which demonstrated the potential of gfi1 as a dominant oncogene and its ability to synergize with pim gene." (PMID 24860787, 2014). "Growth factor independent-1 (Gfi1) is a transcriptional repressor originally identified as a common proviral insertion site of the murine Moloney leukemia virus (MMLV) that conferred IL-2 independent growth to IL-2 dependent T-cell lymphomas." (PMID 24068942, 2013).
acute promyelocytic leukemia (3 papers, 2019 to 2022). An aggressive form of acute myeloid leukemia (AML), characterized by arrest of leukocyte differentiation at the promyelocyte stage, due to a specific chromosomal translocation t(15;17) in myeloid cells. "Drugs that initiate myeloid differentiation are already used in therapy to treat promyelocytic leukemia and a restoration of reduced GFI1 expression to normal levels would have a similar and potentially therapeutic effect." (PMID 29925903, 2019). "GFI1 has also been proposed to be functionally important in acute promyelocytic leukemia (APL)." (PMID 36171271, 2022).
breast tumors (3 papers, 2009 to 2020). "Gfi1 was methylated in 51% of prostate tumor samples (n = 39) recapitulating our previous findings, and in 40% of the primary breast tumors analyzed (n = 44)." (PMID 32630147, 2020). "Gfi1 also interacts with CBFA2T3, a transcriptional repressor that belongs to the ETO family of proteins and has been proposed as a putative breast tumor suppressor gene." (PMID 32630147, 2020).
Burkitt lymphoma (3 papers, 2013 to 2024). A rare form of malignant mature B-cell non-Hodgkin lymphoma. "We next examined whether Gfi1 upregulated Hemgn in murine myeloid 32D and human Burkitt's lymphoma Ramos cells transduced with the Dox-inducible Gfi1-expressing lentiviral construct." (PMID 39374784, 2024).
COVID-19 (3 papers, 2022 to 2025). A disease caused by infection with severe acute respiratory syndrome coronavirus 2. "The rs115545251 locus, located near the GFI1 gene, is linked to hospitalized COVID-19 cases, with colocalization analysis confirming its association with lymphocyte count." (PMID 40034745, 2025). "GFI1, ZNF90, E2F8, E2F2, and EZH2 were also specific to exhausted T cells and may play a vital role in TEX in severe COVID-19." (PMID 35694714, 2022).
melanoma (3 papers, 2016 to 2023). A malignant, usually aggressive tumor composed of atypical, neoplastic melanocytes. "Next, we assessed the α-GalCer-dependent anti-tumor activity in Gfi1-deficient mice using the experimental lung metastasis model of B16 melanoma as previously reported." (PMID 27284976, 2016). "Among the few endogenous miRNAs upregulated in miR-576-5p transfected melanoma cells, we detected miR-548f which targets GFI1, representing a transcriptional repressor of MCL1." (PMID 30197759, 2018). "However, the administration of α-GalCer into Gfi1-deficient mice failed to inhibit lung metastasis of B16 melanoma cells." (PMID 27284976, 2016). "LASSO regression analysis was used to filter TFs further in order to identify a biomarker that could predict the prognosis of patients with melanoma, based on which seven TFs (TBX21, MYB, GFI1, NFE2L3, TFAP2C, HEY2, NR2F2) were selected." (PMID 37435067, 2023).
myeloid malignancies (3 papers, 2020 to 2021). "Our previous investigations and observations have underscored a role for GFI1-36S and -36N SNP variants in myeloid malignancies." (PMID 34760702, 2021). "This corresponds to our previous observations in GFI1-36N myeloid malignancies, whereby GFI1-36N failed to induce epigenetic changes to the same extent as the GFI1-36S protein." (PMID 34760702, 2021).
Obesity (3 papers, 2019 to 2025). Accumulation of substantial excess body fat. "Both in vivo and in vitro experiments further suggested that this downregulation of ACOD1 in obesity may be linked to the upregulation of the transcriptional repressor GFI1 in alveolar macrophages." (PMID 39921443, 2025). "In conclusion, this study demonstrated that in the context of obesity, GFI1 protein levels are significantly elevated in alveolar macrophages, leading to the suppression of ACOD1 expression." (PMID 39921443, 2025). "In summary, these findings indicate that GFI1 suppresses ACOD1 transcription in the lungs in the context of obesity, exacerbating LPS‐induced lung injury, inflammation, and oxidative stress." (PMID 39921443, 2025). "In the context of obesity, GFI1 overexpression may disrupt this balance, leading to abnormal transcriptional repression and immune dysregulation." (PMID 39921443, 2025). "Additionally, in the context of obesity, growth factor independent 1 (GFI1) protein levels are elevated in alveolar macrophages, and its knockdown leads to upregulated ACOD1 expression." (PMID 39921443, 2025). "To further elucidate the role of GFI1 in regulating pulmonary ACOD1 expression in the context of obesity, we specifically knocked down GFI1 expression in the lungs of HFD mice via airway administration of adeno‐associated virus (shGFI1, 5 × 1012 vg ml−1; 100 μl mouse−1, 5 × 1011 vg mouse−1)." (PMID 39921443, 2025). "Therefore, this study suggests that ACOD1 downregulation in alveolar macrophages is a key factor in worsening ALI in obesity, likely driven by GFI1 upregulation." (PMID 39921443, 2025). "This suggests that GFI1 regulation may involve post‐translational modifications, reflecting a complex regulatory mechanism in obesity." (PMID 39921443, 2025). "Further animal experiments revealed that GFI1 knockdown increased ACOD1 expression and alleviated LPS‐induced inflammation in obesity, indicating the critical role of GFI1 in exacerbating lung injury." (PMID 39921443, 2025). "Airway‐targeted knockdown of GFI1 restores ACOD1 expression in the lungs and partially alleviates the worsening of LPS‐induced lung injury in obesity." (PMID 39921443, 2025). "In obesity, reduced ACOD1 expression in AMs worsens LPS-induced lung injury, possibly due to increased GFI1, a transcriptional repressor." (PMID 41039310, 2025).